PTH (parathyroid hormone)
Diseases named in the same sentence as PTH in open-access papers (continued):
Sharing a sentence is not in itself a finding about the gene and the disease.
primary hyperparathyroidism (624 papers, 2004 to 2026). "Bifidobacterium longum, TNF+ T cells, and Th17 cells were mediators of bone loss in primary hyperparathyroidism patients, while Bifidobacterium longum supplementation caused PTH to expand TNF+ T cells and Th17 cells and induce bone loss in mice." (PMID 42185250, 2026). "Primary hyperparathyroidism (PHP) is an endocrine disease caused by excessive secretion of parathyroid hormone (PTH) from the parathyroid glands, caused by a solitary parathyroid adenoma in 80–85% of cases." (PMID 40272707, 2025). "Primary hyperparathyroidism (pHPT) is a common endocrine disorder caused by excessive parathyroid hormone (PTH) secreted from hyperplastic parathyroid tissues." (PMID 40881643, 2025). "Primary hyperparathyroidism, characterized by excessive parathyroid hormone secretion, is typically caused by solitary parathyroid adenomas or multiglandular disease." (PMID 40642222, 2025). "Primary hyperparathyroidism (PHPT) is characterized by elevated or inappropriatelynormal levels of parathyroid hormone (PTH) associated with increased serum calciumconcentrations." (PMID 40893023, 2025). "Renal hypophosphatemia, depending on the mechanism, is divided into PTH-dependent (e.g., primary hyperparathyroidism), FGF23-dependent (e.g., X-linked hypophosphatemia), and intrinsic renal hypophosphatemia (e.g., Fanconi syndrome)." (PMID 41008628, 2025). "Primary hyperparathyroidism (PHPT) is a common endocrine disease caused by oversecretion of parathyroid hormone (PTH), most commonly from a single parathyroid adenoma." (PMID 41181161, 2025). "Brown tumors are rare osteolytic bone lesions linked to primary hyperparathyroidism (pHPT), caused by excessive parathyroid hormone (PTH) production." (PMID 40657234, 2025). "It is the higher PTH levels, instead of the calcium levels, however, that correlates with higher all-cause and cardiovascular morbidity and mortality in untreated primary hyperparathyroidism." (PMID 40608198, 2025). "One of them is primary hyperparathyroidism caused by a parathyroid gland dysfunction (such as adenoma or hyperplasia), responsible for the continuous secretion of parathyroid hormone (PTH), resulting in bone remodeling." (PMID 40267007, 2025). "The lab findings pointed out a normocalcemic primary hyperparathyroidism (PTH of maximum 163 pg/mL, and total calcium of 9.3 mg/dL) caused by a right parathyroid tumor of 1.2 cm, as confirmed by computed tomography (CT)." (PMID 40981138, 2025). "Characterised by hypersecretion of parathyroid hormone (PTH) relative to serum calcium concentration, primary hyperparathyroidism is most commonly caused by sporadic hyperfunctioning parathyroid adenomas, carcinomas or gland hyperplasia." (PMID 39839692, 2025). "Despite their rarity, these tumors are important to recognize due to their association with primary hyperparathyroidism, often presenting with elevated calcium and PTH levels." (PMID 41018270, 2025). "Primary hyperparathyroidism (pHPT) is an endocrine disorder caused by excess parathyroid hormone (PTH) secretion by single or multiple parathyroid glands." (PMID 40642222, 2025). "Normocalcemic Primary Hyperparathyroidism (NPHPT) is a complex syndrome that causes excess secretion of parathyroid hormone (PTH) from the parathyroid glands." (PMID 39582410, 2025). "Brown tumors can mimic multiple skeletal metastases, but elevated calcium and PTH levels typically suggest primary hyperparathyroidism as the underlying cause." (PMID 40145009, 2025). "Preoperative serum intact PTH values are associated with tumor volume of the responsible lesion in primary hyperparathyroidism." (PMID 38525667, 2025). "Excessive production of parathyroid hormone (PTH) from enlarged parathyroid glands causes primary hyperparathyroidism (pHPT)." (PMID 39764345, 2025). "Primary hyperparathyroidism (HPT) is a common endocrine disorder caused by the autonomous overproduction of parathyroid hormone (PTH) from hyperfunctioning parathyroid glands." (PMID 40377436, 2025).
primary hyperparathyroidism (continued). "While primary hyperparathyroidism is the most likely cause when you are dealing with raised PTH levels, a suppressed PTH level warrants a prompt workup for malignancy based on the clinical presentation." (PMID 39434928, 2024). "Chronic elevation of PTH can be caused by conditions such as primary hyperparathyroidism, which is characterized by an overproduction of PTH due to a benign tumor in one or more of the parathyroid glands." (PMID 39200293, 2024). "Primary hyperparathyroidism is a disease caused by excessive secretion of parathyroid hormone (PTH) by the parathyroid glands." (PMID 39764463, 2024). "Primary hyperparathyroidism (PHPT) is an endocrinopathy associated with the autonomous hypersecretion of parathyroid hormone (PTH) from one or more parathyroid glands, resulting in dysregulated calcium homeostasis." (PMID 38192532, 2024). "Primary hyperparathyroidism (PHPT) is a common endocrine disorder of 0.1-0.7% of the general population caused by excess parathyroid hormone (PTH) production." (PMID 39712793, 2024). "FGF23 is increased in patients with primary hyperparathyroidism or activating mutations of PTH or the PTH receptor and by continuous PTH infusion, but it is decreased by intermittent PTH infusion to promote bone anabolism and, sometimes, in hypoparathyroidism." (PMID 38731904, 2024). "When discussing the topic of parathyroid hormone, it should be noted that primary hyperparathyroidism caused by parathyroid hyperplasia or parathyroid adenoma is also possible in oncological patients." (PMID 38920679, 2024). "Background and Objectives: Primary hyperparathyroidism (pHPT) is a common endocrine disorder caused by excessive production of parathyroid hormone (PTH) leading to elevated calcium levels." (PMID 38541233, 2024). "Parathyroid adenoma is a benign parathyroid gland tumor that causes excessive parathyroid hormone production, leading to primary hyperparathyroidism." (PMID 38024058, 2023). "Primary hyperparathyroidism (PHPT) is an excessive parathyroid hormone (PTH) production disorder, causing increased calcium levels." (PMID 37404402, 2023). "Primary hyperparathyroidism (PHPT) is a relatively common endocrine disease caused by excessive secretion of parathyroid hormone (PTH) by pathologically altered parathyroid glands." (PMID 37465121, 2023). "Primary hyperparathyroidism (PHPT) is a common endocrine disorder caused by excess parathyroid hormone (PTH) production." (PMID 36563301, 2023). "Primary hyperparathyroidism (pHPT) is an endocrine disorder caused by inappropriate excess production of parathyroid hormone (PTH) with an annual prevalence ranging between 0.2% and 1% within the United States, according to a 2010 study." (PMID 37370696, 2023). "Primary hyperparathyroidism, an endocrinological disorder characterized by high calcium and inappropriately elevated parathyroid hormone (PTH), is associated with a heightened cardiovascular risk profile." (PMID 37350980, 2023). "Primary hyperparathyroidism (pHPT) is a common endocrine disease caused by improper secretion of parathyroid hormone (PTH), leading to increased serum calcium levels." (PMID 37415163, 2023). "These actions restore serum calcium to the normal set point and lower serum PTH, but if PTH levels remain chronically high, as in the human condition of primary hyperparathyroidism, pathological bone loss ensues." (PMID 36729662, 2023). "Primary hyperparathyroidism (pHPT) is a common endocrine disease caused by excessive secretion of parathyroid hormone (PTH) from one or more hyperfunctioning parathyroid glands." (PMID 37181366, 2023). "Primary hyperparathyroidism is a disease caused by overactive secretion of PTH characterized by hypercalcemia, hypophosphatemia, symptoms of osteoporosis, kidney stones, and numerous neurologic and cardiovascular disorders." (PMID 36389124, 2022).
primary hyperparathyroidism (continued). "Primary hyperparathyroidism is a disease caused by the secretion of excess parathyroid hormone (PTH) owing to the enlargement of the parathyroid gland." (PMID 35987641, 2022). "Primary hyperparathyroidism (PHPT) is a significant endocrine disease caused by increased production of parathyroid hormone (PTH) by altered parathyroid glands and violation of the mechanisms of regulation of serum calcium concentrations." (PMID 36689712, 2022). "Primary hyperparathyroidism (PHPT) is caused by the secretion of excess parathyroid hormone (PTH) owing to the enlargement of the parathyroid gland." (PMID 35987641, 2022). "Primary hyperparathyroidism (pHPT) is an endocrine disease caused by parathyroid hormone (PTH) producing adenoma or hyperplasia in one or more of the 4 parathyroid glands." (PMID 34991581, 2022). "These tumors are most often associated with PTH overproduction, determining the clinical features of primary hyperparathyroidism (pHPT)." (PMID 34638805, 2021). "Primary hyperparathyroidism (PHPT) is an endocrine disease caused by excessive secretion of parathyroid hormone (PTH) from one or more of the four parathyroid glands, manifesting elevated or normal serum calcium levels." (PMID 34925241, 2021). "Positive associations between MPV and PTH were described in individuals with primary hyperparathyroidism and end-stage renal failure patients." (PMID 34222377, 2021). "Primary hyperparathyroidism (PHPT) is caused by inappropriate secretion of parathyroid hormone (PTH) from parathyroid gland." (PMID 33910638, 2021). "Typically evidenced by elevated serum calcium, primary hyperparathyroidism (HPT) is a disorder of mineral metabolism caused by the inappropriate or excessive secretion of parathyroid hormone (PTH) from one or several abnormal parathyroid glands." (PMID 33716975, 2021). "Tumors of the parathyroid glands are the second most frequent endocrine tumors and are often associated with parathormone (PTH) hypersecretion, determining primary hyperparathyroidism (PHPT)." (PMID 34199594, 2021). "The diagnostic challenge was to distinguish primary hyperparathyroidism from ectopic PTH production in a colorectal bone metastasis or potentially another tumor." (PMID 33413267, 2021). "Another study showed PTH as an independent predictor of aortic valve calcification in primary hyperparathyroidism patients after adjusting for risk factors." (PMID 32213826, 2020). "Autonomous production of PTH is the characteristic of primary hyperparathyroidism and this has been associated with various malignancies, as well as with premature death in malignant disorders." (PMID 32983662, 2020). "Primary hyperparathyroidism (PHPT) is a common endocrine disorder that is caused by excessive or inappropriate parathyroid hormone (PTH) secretion with simultaneous derangement of both phosphate and calcium metabolism." (PMID 32621588, 2020). "The most common cause of primary hyperparathyroidism is parathyroid adenoma causing the hypersecretion of parathyroid hormone (PTH)." (PMID 31359305, 2019). "Primary hyperparathyroidism (PHP) is a common endocrine disorder caused by overactivation of one or more parathyroid glands resulting in inappropriate secretion of parathyroid hormone (PTH) by calcium (Ca) level." (PMID 31427650, 2019). "Parathyroid adenoma is the main cause of primary hyperparathyroidism, which is characterized by enlarged parathyroid glands and excessive parathyroid hormone secretion." (PMID 30832348, 2019). "Primary hyperparathyroidism (PHPT) is a common hypercalcemic disorder caused by abnormally increased secretion of parathyroid hormone (PTH) by one or more parathyroid glands." (PMID 31365627, 2019). "Giant parathyroid adenoma is a rare cause of primary hyperparathyroidism and usually presents symptomatically with high calcium and parathyroid hormone levels." (PMID 31722742, 2019).
primary hyperparathyroidism (continued). "Characteristics of studies included in the meta-analysis for the relationship between CaSR rs1801725 gene polymorphism and PTH level in primary hyperparathyroidism patients." (PMID 29794776, 2018). "Primary hyperparathyroidism (PHPT) is caused by an inappropriate elevation of parathormone (PTH) level by one or more glands, which usually results in hypercalcemia." (PMID 28596785, 2017). "Parathyroidectomy (PTX) in patients with primary hyperparathyroidism (PHPT) lowers the level of PTH and leads to the reduction of risk of cardiovascular and all-cause mortality by normalization of the antioxidant status." (PMID 28596785, 2017). "Because primary hyperparathyroidism is associated with poor cardiovascular outcome, a role in cardiovascular disease has been attributed also to the parathyroid hormone (PTH)." (PMID 29056965, 2017). "The link between PTH levels and increased body fat is supported by the evidence of increased body weight in primary hyperparathyroidism and by the positive association with BMI." (PMID 29149839, 2017). "Primary hyperparathyroidism is characterized by hypersecretion of PTH, which is caused by adenomas in 85% of all cases." (PMID 26881146, 2016). "Primary hyperparathyroidism is defined as an elevated PTH level caused by increased production from an adenoma, benign tumor, or malignant tumor of the parathyroid glands." (PMID 27340578, 2016). "Primary hyperparathyroidism is a common endocrine disease, and more than 80% of patients have solitary adenomas, which cause long-term and excess secretion of parathyroid hormone (PTH)." (PMID 27737322, 2016). "Most cases of primary hyperparathyroidism are caused by excessive secretion of intact PTH from parathyroid adenoma or parathyroid hyperplasia." (PMID 27056365, 2016). "The tumor is mostly functioning, causing severe primary hyperparathyroidism, with high serum calcium and parathyroid hormone (PTH) levels." (PMID 26350418, 2015). "Parathyroid adenomas, the most common cause of primary hyperparathyroidism, are benign tumours which autonomously produce and secrete parathyroid hormone." (PMID 26834518, 2015). "Decreased serum sclerostin levels were also shown in patients with high PTH concentration caused by primary hyperparathyroidism; on the contrary in hypoparathyroidism sclerostin levels were high." (PMID 26366174, 2015). "Only two studies provided evidence to support an association between higher PTH levels and poorer cognitive function in primary hyperparathyroidism." (PMID 26010883, 2015). "In patients with primary hyperparathyroidism, smoking was associated with lower PTH and higher phosphate levels." (PMID 25514572, 2014). "At least three studies showed a weak positive correlation between the risk of acquiring breast cancer and primary hyperparathyroidism, a state with high levels of PTH and often high levels of calcium." (PMID 29805904, 2014). "Increasing evidence suggests the bidirectional interplay between parathyroid hormone and aldosterone as an important mechanism behind the increased risk of cardiovascular damage and bone disease observed in primary hyperparathyroidism." (PMID 22974443, 2012). "Increased frequencies of hyperuricemia and gout have been associated with primary hyperparathyroidism, and recent clinical trials of parathyroid hormone (PTH) have reported hyperuricemic adverse events." (PMID 22405053, 2012). "For children in whom primary hyperparathyroidism is suspected, evaluation of serum calcium and PTH levels are the diagnostic tests of choice." (PMID 23227372, 2012). "Primary hyperparathyroidism is a common endocrine disorder characterized by elevated parathyroid hormone levels, which cause continuous osteoclastic bone resorption." (PMID 22204520, 2011). "Primary hyperparathyroidism was diagnosed based on mild elevation of calcium (10.4 mg/dl) associated with a high level of PTH (71,2 pg/ml)." (PMID 20108468, 2008).
primary hyperparathyroidism (continued). "Primary hyperparathyroidism (PHPT) is an endocrine disorder caused by excessive secretion of parathyroid hormone (PTH), which, under physiological conditions, maintains calcium and phosphate homeostasis through its actions on bone, kidneys, and the gastrointestinal tract." (PMID 41293386, 2025). "Additionally, unintended manipulation of parathyroid adenomas during surgery for primary hyperparathyroidism can frequently cause “PTH spikes,” complicating the interpretation of intraoperative PTH monitoring." (PMID 39831132, 2025). "Primary hyperparathyroidism (pHPT) is a common endocrine disorder linked to elevated parathyroid hormone and calcium levels, which may contribute to increased cardiometabolic risk." (PMID 41269693, 2025). "In addition, MCP-1 levels have been positively associated with PTH levels in primary hyperparathyroidism patients and have been reported to be markedly and promptly decreased after PTX." (PMID 40177730, 2025). "In addition, in individuals with primary hyperparathyroidism, the mean carotid intima-media thickness is significantly increased, and higher PTH levels are associated with worse carotid stiffness, reduced carotid strain and decreased distensibility." (PMID 41050279, 2025). "Following this initial presentation, in February 2022, she underwent further diagnostic work-up by the surgical team that confirmed primary hyperparathyroidism, with serum intact PTH level exceeding 2,500 pg/mL (>265 pmol/L) (reference: 12-88 pg/mL (1.27-9.33 pmol/L))." (PMID 39478762, 2024). "Furthermore, other data including systolic blood pressure, 24-h pulse wave velocity, 5.1-fold positive coronary artery calcification score, and left ventricular mass index were associated with serum PTH level in patients with primary hyperparathyroidism." (PMID 37424030, 2023). "For example, chronic overdose of PTH caused by primary hyperparathyroidism or secondary calcium deficiency could increase the rate of bone remodeling and lead to bone loss, while interval administration of PTH could promote bone formation." (PMID 34978631, 2022). "Therefore, it is probable that obesity predisposes to the incidence of primary hyperparathyroidism, but it is unlikely that obesity is the result of the PTH anabolic effect on adipose tissue." (PMID 34422722, 2021). "Moreover, prospective human studies and studies among patients with primary hyperparathyroidism reported that it was also the evaluated PTH that was associated with increased risk of diabetes." (PMID 33833796, 2021). "Excessive secretion of PTH can cause primary hyperparathyroidism (PHPT)." (PMID 32973674, 2020). "Therefore, the present case was extremely rare to be associated with primary hyperparathyroidism, because serum calcium and PTH levels were high." (PMID 25821626, 2015). "A previous study found 30 cases (0.6%) with normal serum calcium and inappropriately high serum PTH (normocalcemic primary hyperparathyroidism) in 5202 subjects, using the diagnostic criteria including serum calcium 2.50-2.60 mmol/l with PTH ≥ 35 ng/L and calcium < 2.50 mmol/l with PTH > 55 ng/L." (PMID 25924883, 2015). "Furthermore, lithium is listed as one of the causes of primary hyperparathyroidism, a biochemical syndrome characterized by increased secretion of parathyroid hormone (PTH) from one or more of the parathyroid glands." (PMID 25505674, 2013). "Elevated levels of calcium and parathyroid hormone (PTH), characteristics of primary hyperparathyroidism (PHPT), may be associated with cardiovascular morbidity and mortality in the general population." (PMID 22815708, 2012). "Importantly, normal PTH and/or PTHrP levels in our patient exclude the possibility of coexisting primary hyperparathyroidism and ectopic secretion of PTH and/or PTHrP caused by tumor cells." (PMID 21970715, 2011).